CFTR (CF transmembrane conductance regulator)
Diseases named in the same sentence as CFTR in open-access papers (continued):
Sharing a sentence is not in itself a finding about the gene and the disease.
inflammatory bowel disease (5 papers, 2022 to 2025). A spectrum of small and large bowel inflammatory diseases of unknown etiology. "A protective role of CFTR loss-of-function mutations in inflammatory bowel disease (IBD) has been suggested, but its evidence has been inconclusive and contradictory." (PMID 41330381, 2025). "Uroguanylin (encoded by GUCA2B) could bind to the guanylate cyclase-C receptor and activate the CFTR to regulate the fluid secretion and exhibit the downregulated expression in inflammatory bowel disease." (PMID 35511361, 2022).
intestinal tumor (5 papers, 2016 to 2023). "The CFTR gene has been shown to be a tumour suppressor gene in animal studies, where loss of CFTR is associated with intestinal tumour formation." (PMID 37524505, 2023). "A latest study found that CFTR mutation increased intestinal tumor multiplicity in Apcmin mice." (PMID 27588407, 2016). "Although the exact mechanism is unclear, intestinal tumor tissue analysis of CFTR knockout mice showed increased β-catenin levels and revealed a functional implication of CFTR in WNT pathway regulation." (PMID 35216222, 2022). "Of further interest, >60% of mice that were mutant for CFTR alone (Apc wildtype) developed intestinal tumors when aged to one year, a phenotype not observed in CFTR wildtype mice." (PMID 35743652, 2022).
melanoma (5 papers, 2011 to 2022). A malignant, usually aggressive tumor composed of atypical, neoplastic melanocytes. "We have presented evidence showing that GSH is released from highly metastatic B16-F10 melanoma cells through MRP1 and the cystic fibrosis transmembrane conductance regulator (CFTR)." (PMID 24212662, 2011). "We observed a high frequency of melanoma and skin cancers among non-transplanted patients, whereas studies published in the 1990s have suggested a possible protective role for CFTR in CF patients without transplant on melanoma." (PMID 36483264, 2022). "Since CFTR clusters form spontaneously in HBE cells we used M2 and A7 cells (neural crest-derived melanoma cell lines without and with filamin A, respectively) to examine the effects of detergent on clustering." (PMID 35060604, 2022).
nasopharyngeal carcinoma (5 papers, 2016 to 2022). A carcinoma arising from the nasopharyngeal epithelium. "The exact mechanisms for the effect of CFTR on nasopharyngeal carcinoma metastasis and prognosis warrant further investigation." (PMID 27769067, 2016). "While there is an increasing interest in the correlation of cystic fibrosis transmembrane conductance regulator (CFTR) and cancer incidence, the role of CFTR in nasopharyngeal carcinoma (NPC) development remains unknown." (PMID 27769067, 2016).
Pendred syndrome (5 papers, 2019 to 2026). Pendred syndrome (PDS) is a clinically variable genetic disorder characterized by bilateral sensorineural hearing loss and euthyroid goiter. "While our results suggest that SLC26A4-mediated HCO3– secretion would be beneficial for CF airways, other studies have implicated this transporter in fluid absorption, as shown in airway cells from patients with Pendred Syndrome, where the SLC26A4 gene is mutated, but CFTR is still active." (PMID 37967223, 2023).
Tangier disease (5 papers, 2005 to 2024). "CFTR-/- mφs were alkaline at baseline, a characteristic that was increased with iron-overload." (PMID 35887506, 2022).
autoimmune disease (4 papers, 2014 to 2026). A disorder resulting from loss of function or tissue destruction of an organ or multiple organs, arising from humoral or cellular immune responses of the individual to their own tissue constituents. "Although histological changes of the pancreas related to ETI treatment are not yet defined in humans, improved acinar structure, correction of ductal CFTR activity has been shown to reduce ductal obstruction and inflammatory infiltration in animal model of autoimmune disease." (PMID 41134303, 2026). "Altered permeability of the intestinal barrier together with decreased expression of CFTR and increased expression/activity of TG2 observed in patients affected by CD upon gluten consumption is followed by inflammation and immune system activation, finally resulting in autoimmune disease onset." (PMID 33712560, 2021).
cataract (4 papers, 2018 to 2025). Partial or complete opacity of the crystalline lens of one or both eyes that decreases visual acuity and eventually results in blindness. "Thus, it is advisable that infants exposed to CFTR modulators in utero or through breast milk undergo formal examination for cataracts." (PMID 32825766, 2020). "Additional adverse events seen with other CFTR modulators included increased aminotransferases, rash, and cataracts: these events were not serious and none led to drug interruption or discontinuation." (PMID 39756425, 2025). "Despite the lack of data on in utero drug exposure, a case report described two babies born from mothers receiving CFTR modulators without any evidence of congenital malformations or cataracts." (PMID 36015300, 2022). "If a mother chooses to continue using CFTR modulators during pregnancy and lactation, the development of non-congenital cataracts in juvenile rats and case reports in pediatric patients treated with modulators suggest the need for infant ophthalmologic exams." (PMID 32825766, 2020). "Because cases of non-congenital lens opacities have been reported in pediatric patients treated with CFTR modulators, it is recommended that pediatric patients who are treated with these agents undergo baseline and follow-up ophthalmological examinations." (PMID 32825766, 2020).
cryptorchidism (4 papers, 2017 to 2022). The failure of one or both testes of a male fetus to descend from the abdomen into the scrotum during the late part of pregnancy. "In only four (~5%) of the men with histologically abnormal testicular tissue, a CFTR mutation was detected, and one of these men in addition had a history of cryptorchidism and one a varicocele." (PMID 30565706, 2019). "This may be due to referral of an increased number of men with KS (P = .002, χ2‐test), while a trend for reduced proportions of azoospermic men with a history of cryptorchidism or CFTR mutations was observed." (PMID 33095972, 2021). "Consequently, it was proposed that the elevated testicular temperature in cryptorchidism might cause a spermatogenic defect by impairing CFTR function, which in turn, might up-regulate the COX20 pathway and disrupt the blood-testis barrier." (PMID 35725394, 2022). "We propose that, in boys with cryptorchidism, CFTR expression is controlled by luteinizing hormone and testosterone." (PMID 35725394, 2022). "Interestingly, we found a very high association between presence of the CFTR intron variant IVS8‐5T and a history of cryptorchidism requiring orchiopexia, which has to be further investigated in up‐coming studies." (PMID 33095972, 2021). "The inverse relationship between CFTR and NFκB has also been found in male reproductive tract, where high temperature-downregulated CFTR with upregulated NFκB/COX2/PGE2 was found to be responsible for impaired testis-blood barrier, and thus disrupted spermatogenesis as seen in cryptorchidism." (PMID 28978008, 2017).
endometriosis (4 papers, 2017 to 2021). The growth of functional endometrial tissue in anatomic sites outside the uterine body. "Of interest, CFTR has been implicated in the pathogenesis of endometriosis by a proteomic study together with 20 proteins identified." (PMID 28978008, 2017). "Although the exact mechanism underlying the regulatory effect of CFTR on uPAR awaits further investigation, the present finding offers a potential diagnostic strategy for endometriosis targeting both CFTR and uPAR." (PMID 28978008, 2017). "The present findings warrant future investigation of diagnostic and treatment strategies for endometriosis targeting CFTR and related signaling." (PMID 28978008, 2017). "Taken together, these data suggest a potentially pivotal role of ion channels such as CFTR, AQPs, and ClC-3 in the complex and multifactorial pathogenesis of endometriosis." (PMID 32046116, 2020). "Similar to the finding from previous reports, the present study also detected upregulated NFκB in the human endometriotic lesions exhibiting high levels of CFTR and uPAR, confirming a positive relationship between CFTR and NFκB in endometriosis." (PMID 28978008, 2017). "This is consistent with the important role of CFTR in cell migration and thus progression of endometriosis demonstrated in the present study." (PMID 28978008, 2017). "The CFTR-dependent signaling pathways involved in the cancers studied and endometriosis appear to be different." (PMID 28978008, 2017). "The demonstrated role of CFTR in cell migration, together with dependence of CFTR expression on estrogen, provides a novel insight into the pathogenesis of endometriosis." (PMID 28978008, 2017). "The present finding, therefore, suggests that targeting CFTR or its signaling (such as NFκB and uPAR) may be attractive alternatives for the intervention of endometriosis." (PMID 28978008, 2017). "Collectively, the present results suggest that the CFTR-NFκB-uPAR signaling may contribute to the progression of human endometriosis, and indicate potential targets for diagnosis and treatment." (PMID 28978008, 2017). "In the present study, we explored whether CFTR plays a role in the development of human endometriosis." (PMID 28978008, 2017). "In other words, the pathological progression of endometriosis may be triggered by abnormal estrogen-stimulated CFTR expression in the endometrium." (PMID 28978008, 2017). "Therefore, the clinically offered hormonal treatments for endometriosis could be mediated by the hormonal effect on CFTR downregulation." (PMID 28978008, 2017). "Given the presently observed correlation of CFTR and uPAR expression in human endometriosis and the well-established role of uPAR in cell invasion/migration and its regulation by NFκB, we explored the involvement of NFκB in mediating the effect of CFTR on uPAR expression and cell migration." (PMID 28978008, 2017). "The upregulated expression of CFTR in female tract cancers and its interaction with NFκB, and the fact that uPAR is positively regulated by NFκB singling, led us to the hypothesis that CFTR might be involved in the progression of endometriosis by promoting NFκB and uPAR-dependent cell migration." (PMID 28978008, 2017). "However, quantified expression level of CFTR in human endometriosis has not been confirmed and its exact role in the development of endometriosis remains unexplored." (PMID 28978008, 2017). "The present results indicate that aberrantly high expression of CFTR, but not its channel function, and abnormally high uPAR expression confer a propensity of exaggerating cell migration that leads to the progression of endometriosis." (PMID 28978008, 2017).
esophageal cancer (4 papers, 2020 to 2023). A primary or metastatic malignant neoplasm involving the esophagus. "Several studies have reported that CFTR dysfunction is associated with the development and progression of esophageal cancers, both esophageal squamous cell carcinoma (ESCC) and esophageal adenocarcinoma (EAC), and all studies support a tumor suppressing role for CFTR." (PMID 35743652, 2022). "Studies in recent years have shown that V-ATPase and CFTR not only play important roles in the tumorigenesis and progression of many cancers, such as esophageal cancer, but also are involved in distal renal tubular acidosis." (PMID 36980869, 2023). "In addition, CFTR was shown to inhibit invasion by suppressing NFκB in esophageal cancer cells." (PMID 32182826, 2020).
glioblastoma (4 papers, 2016 to 2023). The most malignant astrocytic tumor (WHO grade IV). "More importantly, the protein expression level of CFTR is significantly increased in glioblastoma patient samples." (PMID 32463592, 2020). "While we do not find a significant difference in the expression level between normal brain and astrocytoma, the expression levels of CFTR are significantly higher in glioblastoma patients compared to normal brain." (PMID 32463592, 2020). "Of note, CFTR expression showed a relative low to middle intensity in the low‐grade (grade 2‐3) astrocytomas compared to the high‐grade (grade 3‐4 & 4) astrocytomas or glioblastomas." (PMID 32463592, 2020). "Analysis of the networks formed by HF2303 or IN2045 demonstrated a close association of PRKG1 with CFTR, two proteins not yet linked to glioblastoma biology." (PMID 27564115, 2016). "PPI and gene ontology networks examined suggest the existence of further targets to be explored for the treatment of glioblastoma, such as PRKG1, CFTR, PLCB1, and TBX2." (PMID 27564115, 2016). "In summary, our finding showing that CFTR regulates Akt/Bcl2‐mediated anti‐apoptotic pathway, warrants future investigations into the potential of using CFTR as a therapeutic target and exploring combination therapy to target PI3K/Akt pathway in the treatment of glioblastomas." (PMID 32463592, 2020).
Glucose intolerance (4 papers, 2019 to 2025). Glucose intolerance (GI) can be defined as dysglycemia that comprises both prediabetes and diabetes. "As proof of a role of CFTR in human insulin secretion, some authors demonstrated that drugs correcting CFTR dysfunction improve insulin secretion and glucose intolerance after 1–4 months of treatment." (PMID 33810109, 2021).
head and neck cancer (4 papers, 2020 to 2025). A primary or metastatic malignant neoplasm affecting the head and neck. "The present study explored the expression patterns of CFTR in head and neck cancer and in normal cells and tissues." (PMID 32182826, 2020). "Therefore, epigenetic drugs and CFTR inhibition might give good insight into developing promising therapeutic agents for head and neck cancer." (PMID 32182826, 2020).
Klinefelter syndrome (4 papers, 2011 to 2023). A sex chromosome disorder caused by the presence of an extra X chromosome in the male karyotype. "The inclusion of an increasing number of men with Klinefelter's syndrome may have resulted in slightly decreased proportion of men with CFTR mutations over time, which might be considered a minor weakness of the study." (PMID 33095972, 2021).
liver fibrosis (4 papers, 2021 to 2026). "This suggests that CFTR modulators may offer the greatest benefit for patients with more advanced hepatic fibrosis, while their impact may be less pronounced in those with milder disease." (PMID 41362828, 2026).
malaria (4 papers, 2014 to 2025). Malaria is a serious and sometimes fatal disease caused by a parasite that commonly infects a certain type of mosquito which feeds on humans. "The high frequency of mutations in the CFTR gene in European populations and individuals of European descent could be an argument against the dominant role of malaria in the past pathocoenoses." (PMID 25484866, 2014). "Hence, the selective agent(s) for the high frequency of CFTR mutations still remain unclear, but does not contradict the hypothesis of malaria major role in past pathocoenoses." (PMID 25484866, 2014). "In the remote past, declines in CFTR and ARSB may have provided a selective advantage to humans against malaria, since malarial-infected red blood cells bind less well to the endothelium when chondroitin 4-sulfate is more sulfated, implying a survival benefit against malaria from ARSB deficiency." (PMID 40362587, 2025).
Marfan syndrome (4 papers, 2021 to 2025). A disorder of the connective tissue. "The method may also be beneficial for other Mendelian diseases, such as CFTR-related diseases, Tay-Sachs disease, Marfan syndrome, and tuberous sclerosis." (PMID 33546218, 2021).
myocardial infarction (4 papers, 2022 to 2026). Gross necrosis of the myocardium, as a result of interruption of the blood supply to the area, as in coronary thrombosis. "In the rat I/R model, YTHDF3 overexpression increased myocardial infarct size and impaired cardiac function, whereas CFTR overexpression attenuated the injury associated with YTHDF3 overexpression." (PMID 42265766, 2026). "Cerebral cystic fibrosis transmembrane regulator (CFTR) is down-regulated in the brain after myocardial infarction." (PMID 36462404, 2022). "Mice with HF, induced by myocardial infarction, were treated with the CFTR corrector compound C18 starting ten weeks post-myocardial infarction for two consecutive weeks." (PMID 35055052, 2022). "We next tested whether therapeutic correction of CFTR expression in vivo affects pulmonary S1P levels by treating HF mice with the CFTR corrector compound C18, starting 10 weeks post-myocardial infarction." (PMID 35055052, 2022). "Restoring CFTR expression normalises neuronal injury induced by myocardial infarction." (PMID 36462404, 2022).